ABCC1 (ATP binding cassette subfamily C member 1 (ABCC1 blood group))
Diseases named in the same sentence as ABCC1 in open-access papers (continued):
Sharing a sentence is not in itself a finding about the gene and the disease.
tumor (continued). "We analyzed the TCGA-LUAD dataset (n = 585): after excluding 8 cases because of the lack of information about tumor stage and 59 cases classified as “normal tissues”, we analyzed the expression of TFEB, ABCC1 and ABCA1 mRNA in the remaining cohort of 531 cases of primary tumors." (PMID 39107857, 2024). "The average expression level of the ABCA3 (p = 0.007), ABCB9 (p = 0.000), ABCC1 (p = 0.000), ABCC4 (p = 0.000), ABCC5 (p = 0.000), and ABCC6 (p = 0.000) genes was statistically significantly higher in patients without tumor cell infiltration in the lymph vessels." (PMID 36674773, 2023).
infection (4 papers, 2011 to 2025). The state of being infected such as from the introduction of a foreign agent such as serum, vaccine, antigenic substance or organism. "We detected genome-wide significant genetic associations with urinary bacterial relative abundances, in or near candidate genes including CXCL12, ABCC1, and ROBO1, which are implicated in urinary tract development and response to infection." (PMID 41364520, 2025). "Because antigen-dependent activation of iNKT cells is critical for protection of mice from S. pneumoniae, we analyzed activation of iNKT cells after infection and the survival of Abcc1−/− mice." (PMID 30323255, 2018). "Furthermore, Abcc1−/− mice had decreased survival and increased bacteria in their lungs at day 2 after infection." (PMID 30323255, 2018). "To validate findings in this present study of productive infection, we examined all quantified ABC transporters and found selective downregulation of ABCC1 as well as ABCC3." (PMID 24906157, 2014).
neurologic disorders (2 papers, 2021 to 2023). "ABCC1 may also contribute to the drug permeability barrier between the blood and cerebrospinal fluid, a possible reason for ineffective treatment of neurologic disorders." (PMID 37438132, 2023). "Finally, a diverse array of multi-substrate efflux pumps including ABCB1/MDR1 (p-glycoprotein), ABCC1 (MRP1) and BCRP/ABCG2, actively transport unwanted substances back to the luminal side, including most drugs of potential value for neurological disorders." (PMID 34452156, 2021).
adenocarcinoma (1 paper, 2025). A common cancer characterized by the presence of malignant glandular cells. "It is not known if this mechanism is active in vivo, but high pretherapeutic ABCC1 expression in locally advanced adenocarcinomas of the esophagus has been shown to be beneficial for treatment with platinum drugs like cisplatin." (PMID 40357991, 2025).
blood cancer (1 paper, 2022). "The ABCB1, ABCC1, p-AKT, p-NFκB, and NFκB levels were associated with responsiveness to eribulin in blood cancer cells, and a resistance eribulin-related target score was constructed." (PMID 36551566, 2022). "Among these molecular targets, ABCB1 (r = 0.53, p = 0.02), ABCC1 (r = 0.67, p = 0.001), p-AKT (r = 0.53, p = 0.02), p-NFκB (r = 0.80, p < 0.0001), and NFκB (r = 0.81, p < 0.0001) were associated with IC50 values for eribulin in the blood cancer cell lines." (PMID 36551566, 2022).
hematological cancer (1 paper, 2010). "ABCC1 is known to be involved in chemoresistance of hematological cancer stem cells, however it is not obviously down regulated throughout differentiation, questioning its contribution to stem cell integrity." (PMID 20836839, 2010).
peripheral neuropathy (1 paper, 2024). A disorder affecting the peripheral nervous system. "The results indicated that age at diagnosis (OR = 1.33; 95% CI = 1.07–1.75) and the ABCC1 rs246240 G allele (OR = 12.48; 95% CI = 2.26–100.42) were associated with vincristine-induced peripheral neuropathy (VIPN)." (PMID 39201483, 2024).
ABCC1 also shares sentences with these, for which no sentence is quoted: invasive breast carcinoma (3 papers); astrocytoma (2); latent infection (2); Oral squamous cell carcinoma (2); osteoporosis (2); 21-hydroxylase deficiency (1); anaplastic astrocytoma (1); anemia (1); astrocytic tumor (1); atopic dermatitis (1); autism (1); autosomal dominant deafness-77 (1); benign tumors (1); bladder cancer (1); cancers of the brain (1); cardiac diseases (1); cardiovascular diseases (1); childhood cancer (1); diabetes (1); diffuse large B-cell lymphoma (1); fibrosarcoma (1); genetic disorders (1); Glucose intolerance (1); Hodgkins lymphoma (1); hyperlipidemia (1); Insulin resistance (1); Intellectual disability (1); invasive breast ductal carcinoma (1); laryngeal carcinoma (1); liver fibrosis (1).
A further 23 diseases each share a sentence with ABCC1 in 1 paper.